EGFR (epidermal growth factor receptor)
Diseases named in the same sentence as EGFR in open-access papers (continued):
Sharing a sentence is not in itself a finding about the gene and the disease.
non-small cell lung carcinoma (continued). "Sensitizing mutations in the epidermal growth factor receptor (EGFR) predict response to EGFR tyrosine kinase inhibitors (TKIs) and both first- and second-generation TKIs are available as first-line treatment options in patients with advanced EGFR-mutant non-small cell lung cancer." (PMID 28620581, 2017). "Similarly, there have been studies combining CX-4945 with Erlotinib, an EGFR tyrosine kinase inhibitor used to treat advanced or metastatic non-small cell lung cancer." (PMID 28134850, 2017). "Notably, abnormally activated EGFR predicts poor outcomes in many cancer types including non-small-cell lung cancer (NSCLC), head and neck cancer, and breast cancer." (PMID 27902463, 2017). "Epidermal growth factor receptor (EGFR) activating mutations in exons 18–21 and their exceptional responses to its kinase inhibitors marked the beginning of precision medicine in non-small cell lung cancer (NSCLC)." (PMID 29034207, 2017). "The aim of this retrospective study is to identify epidermal growth factor receptor (EGFR) mutations in non-small cell lung cancer patients and to compare the long-term postoperative outcomes in different EGFR-TKI-targeted therapy effects between the different EGFR mutation groups." (PMID 29110716, 2017). "Our study indicates that miR-370 may bind to the 3′UTR of EGFR to inhibit EGFR expression and the growth, angiogenesis and metastasis of non-small cell lung cancer by down-regulating the ERK1/2 and AKT signaling." (PMID 29152147, 2017). "As EGFR-tyrosine kinase inhibitor (TKI) can provide a better efficacy and quality of life to the patients, it has emerged as one of the most important therapies among non-small cell lung cancer (NSCLC) patients harboring activating EGFR mutations." (PMID 27384480, 2016). "We also showed that epidermal growth factor receptor gene (EGFR) mutation-negative non-small cell lung cancer (NSCLC) cells are more resistant to X-rays than EGFR mutation-positive NSCLC cells." (PMID 27376029, 2016). "In non-small cell lung cancer cells, for example, M3Rs activated by ACh promote cell proliferation and invasion via the EGFR/PI3K/AKT pathway, while in colon cancer M3R activation exerts a growth-promoting effect by mediating activation of the p21Ras-ERK pathway through tyrosine-phosphorylated EGFR." (PMID 26919111, 2016). "Detecting epidermal growth factor receptor (EGFR) activating mutations in plasma could guide EGFR-tyrosine kinase inhibitor (EGFR-TKI) treatment for advanced non-small cell lung cancer (NSCLC)." (PMID 27619632, 2016). "For example, Hata and coworkers have recently shown that acquired resistance of epidermal growth factor receptor (EGFR)-mutant non-small-cell lung cancers to anti-EGFR therapy can occur through the genetic evolution of initially EGFRT790M-negative drug-tolerant cells." (PMID 27702751, 2016). "Similarly, we saw that genes downregulated in gefitinib resistant non-small cell lung cancer cells undergoing prominent growth arrest and apoptosis upon treatment with an irreversible EGFR inhibitor, CL-387,785, were enriched in low miR-644a signature scorers." (PMID 27409664, 2016). "In the case of non-small cell lung carcinoma (NSCLC), the presence of defined mutations in the EGFR kinase domain, known as sensitizing mutations, substantially increases the response to treatment with the EGFR-specific small molecule inhibitors erlotinib and gefitinib." (PMID 27248176, 2016). "In non-small cell lung cancer (NSCLC), EGFR is overexpressed due to EGFR amplification or mutation." (PMID 27223277, 2016). "Indeed, two recent reports exemplify this approach by showing promising in vitro data against EGFR-mutant or overexpressed non-small cell lung cancer (NSCLC) and HER2-positive breast cancer." (PMID 27489860, 2016).
non-small cell lung carcinoma (continued). "The first-generation EGFR TKIs, such as erlotinib and gefitinib, and the second-generation EGFR TKIs such as afatinib, have been widely used in the treatment of patients with advanced non-small cell lung cancer (NSCLC)." (PMID 27649127, 2016). "In this study, we restored TUSC2 gene expression in several wild type EGFR non-small cell lung cancer (NSCLC) cell lines resistant to the epidermal growth factor receptor (EGFR) tyrosine kinase inhibitor erlotinib and analyzed their sensitivity to erlotinib in vitro and in vivo." (PMID 26053020, 2015). "Based on previous studies of non-small cell lung cancer, EGFR mutations occurred more common in non-smoking patients." (PMID 26392415, 2015). "Somatic mutations of EGFR in exon 21 (e.g., L858R) and exon 19 deletions have frequently been identified in patients with non-small cell lung cancer (NSCLC) who are frequently non-smokers." (PMID 26027747, 2015). "Although patients with non-small cell lung cancer (NSCLC) experience an initial response to the epidermal growth factor receptor (EGFR) tyrosine kinase inhibitor gefitinib, those individuals with activating mutations in EGFR develop resistance." (PMID 26622796, 2015). "In addition, a recent study demonstrated that miR-27a regulated both EGFR and c-Met in non-small cell lung cancer." (PMID 25405368, 2015). "Therefore, we propose that rosmarinic acid is a good starting point for developing a new type of inhibitors for the treatment of non-small-cell lung cancer with drug-resistant EGFR and rheumatoid arthritis." (PMID 26077136, 2015). "In clinic, Bean reported that Met gene amplification was detected in 22% of acquired EGFR-TKI resistant non-small cell lung cancers, and, compared with patients unexposed to EGFR kinase inhibitor, Gefitinib or Tarceva treatment was more likely to select Met gene amplification (21% versus 3%)." (PMID 25834821, 2015). "CXCR2 is activated by cancer-promoting IL-8 and CXCL1 and could transactivate EGFR in ovarian cancer and non-small cell lung cancer." (PMID 26462152, 2015). "The present study aimed to investigate the association between epidermal growth factor receptor (EGFR) gene mutations and excision repair cross-complementing protein 1 (ERCC1) and ribonucleotide reductase subunit M1 (RRM1) mRNA expression in non-small cell lung cancer (NSCLC) tissue." (PMID 25667646, 2015). "Besides epidermal growth factor receptor (EGFR) mutation, the non-small cell lung cancer (NSCLC) of anaplastic lymphoma kinase (ALK) rearrangement becomes another important clinical subtype." (PMID 25676399, 2015). "EGFR-targeted cancer therapy is a breakthrough in non-small cell carcinoma." (PMID 26593208, 2015). "However, the prognostic significance of LMR in patients with advanced-stage EGFR-mutant non-small cell lung cancer (NSCLC) receiving first-line epidermal growth factor receptor (EGFR)-tyrosine kinase inhibitors (TKIs) has not been established." (PMID 26313661, 2015). "In non-small cell lung cancer cell lines, evolutionary mathematical modeling of tumor behavior demonstrated that optimally timed sequential strategies yielded large improvements in survival outcome with anti-EGFR treatment." (PMID 26474549, 2015). "Initial implementation of this multiplexed SCODA mutation enrichment and detection assay focused on 46 mutations in 4 genes (BRAF, EGFR, KRAS, and PIK3CA), constituting a set of commonly encountered mutations of clinical relevance in colorectal and non-small cell lung cancers." (PMID 25575824, 2015). "Further examples abound in other tumor types, such as the association of ERBB2 and CRKL amplification with resistance to anti-epidermal growth factor receptor (EGFR) targeted agents in non small-cell lung cancer and YAP amplification with resistance to doxorubicin in hepatocellular carcinoma." (PMID 25888249, 2015). "In addition, EGFR inhibitor gefitinib (Iressa) is successful for treating of non-small cell lung cancer." (PMID 26503469, 2015).
non-small cell lung carcinoma (continued). "ZD6474 is a novel VEGFR-2, EGFR and Src tyrosine kinase inhibitor, which suppresses a number of tumors, including non-small cell lung cancer as well as breast, gastric, prostate, colorectal, nasopharyngeal cancers and leukemia, through inhibiting tumor cell growth and survival." (PMID 26050198, 2015). "The identification of epidermal growth factor receptor (EGFR) mutation and anaplastic lymphoma kinase (ALK) rearrangements has changed the treatment of non-small cell lung cancer, creating a personalized treatment era that is based on the appropriate molecular selection of patients." (PMID 25295096, 2014). "Gefitinib, a selective EGFR (ErbB1) tyrosine kinase inhibitor has been approved for the treatment of non-small cell lung cancer.It prevents autophosphorylaton of EGFR resulting in the inhibition of cyclin- dependent kinase activity and cell cycle arrest in the G1 phase." (PMID 25191874, 2014). "It has been shown that a therapeutic effect can be seen after the use of EGFR-inhibitors in non-small cell lung cancers, even if there is no activating mutation in the EGFR gene." (PMID 24934485, 2014). "The molecularly targeted agents, including anti-VEGF or anti-EGFR monoclonal antibody and some inhibitors of EGFR tyrosine kinase, are effective in the treatment of non-small-cell lung cancer (NSCLC) to a certain extent, but the benefit for a proportion of patients is still limited." (PMID 25138052, 2014). "Although seven EGFR mutations were detected, there were no cases with activating EGFR mutations (exon 19 deletion or L858R), which are well-known gene abnormalities in non-small cell lung cancer." (PMID 25343854, 2014). "The systematic review with meta-analysis showed that EGFR mutations were not a prognostic factor in patients with surgically resected non-small cell lung cancer." (PMID 25162713, 2014). "Ludovini reported that if both IGF-IR and EGFR are highly co expressed in resected non-small-cell lung cancer, patients might achieve shorter disease-free survival." (PMID 24618737, 2014). "Gefitinib is a EGFR inhibitor that is used in the treatment non-small cell lung cancer." (PMID 23816254, 2013). "Indeed, EGFR-tyrosine kinase inhibitors (EGFR-TKIs) have been developed and clinically used in patients with malignancy, especially non-small cell lung carcinoma." (PMID 23592411, 2013). "This could also be true for some non-small cell lung cancers in which cPKCs are highly expressed and the downregulation of EGFR is impaired." (PMID 24244711, 2013). "Combination of EGFR tyrokinase inhibitors and NK cells adoptive immunotherapy may represent a potentially effective strategy for patients with non-small cell lung cancer." (PMID 23937717, 2013). "EGFR is frequently over-expressed in non-small cell lung cancers (NSCLC)." (PMID 23937717, 2013). "Therefore, EGFR is one of the molecular targets for the treatment of malignancies, such as non-small cell lung cancer." (PMID 23592411, 2013). "A number of researches demonstrated that overexpressions of EGFR and ErbB-2 has been observed in many cancer patients and correlate with a poor prognosis for several tumors including non-small-cell lung cancer (NSCLC), prostate, breast, stomach, colon, and ovarian cancers." (PMID 23936329, 2013). "Notably, the epidermal growth factor receptor (EGFR) has been demonstrated to be overexpressed in various types of cancer, including non-small-cell lung cancer (NSCLC), and to be involved in the growth of cancer cells." (PMID 23420613, 2013). "This study was designed to determine whether advanced non-small-cell lung cancer (NSCLC) patients with high copy number of epidermal growth factor receptor (EGFR) can benefit from treatment with EGFR-tyrosine kinase inhibitors (TKIs)." (PMID 23557218, 2013).
non-small cell lung carcinoma (continued). "In contrast, Asian non-smoking women have a high incidence of non-small cell lung cancer (NSCLC) associated with an EGFR mutation irrespective of the country where they live, suggesting a germline predisposition for NSCLC with this mutation." (PMID 23708256, 2013). "Our previous study showed that a newly designed tracer radioiodinated 6-(3-morpholinopropoxy)-7-ethoxy-4-(3’-iodophenoxy)quinazoline ([125I]PYK) is promising for the evaluation of the epidermal growth factor receptor (EGFR) status and prediction of gefitinib treatment of non-small cell lung cancer." (PMID 27408849, 2013). "For example, monoclonal antibodies that bind the EGFR extracellular domain can promote downregulation, and the endocytosis of EGFR induced by EGF is closely related to the sensitivity to the tyrosine kinase inhibitor gefitinib in non-small cell lung cancer cell lines." (PMID 23631593, 2013). "In non-small cell lung cancers (NSCLC), EGFR mutations are targeted with Gefitinib and Erlotinib." (PMID 23863689, 2013). "Since the beginning of use of the epidermal growth factor receptor tyrosine kinase inhibitors (EGFR-TKIs) gefitinib and erlotinib for treatment of advanced non-small-cell lung cancer (NSCLC), studies have shown that NSCLC patients with EGFR-activating mutations can benefit from TKI treatment." (PMID 23536868, 2013). "Everolimus is currently used in the treatment of a number of diseases: metastatic renal cancer resistant to sorafenib or sunitinib, non-small cell lung cancer unresponsive to anti-epidermal growth factor receptor (EGFR) therapy, as well as in cardiac or renal transplant patients." (PMID 24245774, 2013). "In epidermal growth factor receptor (EGFR) mutant non-small cell lung cancer cells, MCL-1 downregulation by a PI3K/mTOR kinase inhibitor in combination with BIM upregulation (a pro-apoptotic member of the bcl-2 family) by a MEK inhibitor has been shown to be critical for the induction of apoptosis." (PMID 22808163, 2012). "We evaluated the repercussions of α-tocopherol addition on (i) imatinib and nilotinib treatment, two drugs used to inhibit the oncogenic fusion protein BCR-ABL in CML and (ii) on gefitinib effect, a well described EGFR inhibitor usually prescribed for non-small cell lung cancer." (PMID 22590613, 2012). "Analysis of gene copy numbers of the EGFR has not consistently shown that this mutation is also involved in a larger response to gefitinib in the treatment of non small lung cell cancer after failure of docetaxel--or platinum-based chemotherapy." (PMID 22397594, 2012). "In non-small cell lung cancers sensitive to EGFR tyrosine kinase inhibition is lost usually due to ‘gatekeeper’ mutation however surprisingly acquisition of BRAF gatekeeper ‘mutations’ do not account for secondary drug resistance in melanoma that acquire resistance to BRAF inhibitors." (PMID 25562798, 2012). "EGFR-directed antibodies (cetuximab and panitumumab) and small molecule inhibitors (gefitinib and erlotinib) provide positive therapeutic effects in several types of cancer, including non-small cell lung cancer (NSCLC)." (PMID 22554165, 2012). "Recently, it was reported that Nimotuzumab could substantially improve the radiosensitivity of brain tumor and non-small cell lung cancer cells with high or moderate levels of EGFR." (PMID 23232108, 2012). "In addition to EGFR overexpression, EGFR gene amplification is another common genetic alteration found in glioma, non small cells lung cancers or colorectal tumors." (PMID 22623992, 2012). "It is mandatory to confirm the absence of mutations in the KRAS gene before treating metastatic colorectal cancers with epidermal growth factor receptor inhibitors, and similar regulations are being considered for non-small cell lung carcinomas (NSCLC) and other tumor types." (PMID 22995035, 2012).
non-small cell lung carcinoma (continued). "Similarly, EGFR copy number has been shown to be a predictor of gefitinib related survival benefit in advanced non small cell lung cancer patients." (PMID 23056179, 2012). "In contrast to the HER2-amplified breast tumours, inhibition of PI3K/mTOR signalling non-small cell lung cancers with activating mutations of EGFR did not induce apoptosis." (PMID 21649578, 2011). "On the other hand, in the study of Faber and colleagues, inhibition of PI3K/mTOR signalling in non-small cell lung cancers with activating mutations of EGFR did not induce apoptosis, in contrast to HER2-amplified breast tumours in which sensitivity was seen." (PMID 21649578, 2011). "Furthermore, at low doses it induces apoptosis even of cells that are resistant to the most frequently used EGFR-inhibitors, such as gefitinib and cetuximab, and inhibits tumor growth in a mouse xenograft model of human non-small-cell lung cancer (NSCLC)." (PMID 21915281, 2011). "In the last 6 years, since the first reports of an association between somatic mutations in epidermal growth factor receptor (EGFR) exons 19 and 21 and response to EGFR tyrosine kinase inhibitors (TKIs), treatment of non-small cell lung cancer (NSCLC) has changed dramatically." (PMID 21444946, 2011). "Gefitinib, a tyrosine kinase inhibitor of the epidermal growth factor receptor (EGFR), is beneficial as a drug for treating non-small cell lung cancer; however, this drug induces ILD and the molecular mechanisms underpinning this condition remain unclear." (PMID 22096546, 2011). "Epidermal Growth Factor Receptor (EGFR) mutations, especially in-frame deletions in exon 19 (ΔLRE) and a point mutation in exon 21 (L858R) predict gefitinib sensitivity in patients with non-small cell lung cancer." (PMID 21575212, 2011). "Major results from the EGFR-scores analyses of non-small cell lung cancer (n = 47)." (PMID 20096104, 2010). "Likewise, EGFR is overexpressed in many cancers (non-small cell lung cancer, head and neck cancer, ovarian, colon, bladder, kidney and prostate cancers)." (PMID 27713352, 2010). "Using clinical specimens from patients with non small cell lung cancers that recurred after treatment with EGFR inhibitors, 50% of patients have acquired an additional mutation, T790 M, which creates an EGFR that no longer responds to EGFR inhibition." (PMID 20624308, 2010). "Further investigation has recently revealed that, in patients with non-small cell lung cancer (NSCLC) with mutated EGFR, higher response rates and longer survival time could be achieved with the use of the EGFR tyrosine kinase inhibitor gefitinib." (PMID 20184776, 2010). "Kinase domain mutations of EGFR are found in 30–50% East Asian and 5–10% non-East Asian patients of non-small cell lung cancer." (PMID 20010942, 2010). "Erlotinib (Tarceva; OSI Pharmaceuticals), an inhibitor of the epidermal growth factor receptor (EGFR), is also approved for the treatment of patients with locally advanced or metastatic non-small cell lung cancer and pancreatic carcinoma in combination with gemcitabine." (PMID 19432987, 2009). "It has been previously demonstrated that EGFR TKI, such as erlotinib/or gefitinib treatment with fluoropyrimidine, resulted in an synergistic inhibitory effect in non-small-cell lung cancer cells, possibly as the result of TS downregulation via the inhibition of EGFR signaling." (PMID 19529774, 2009). "Indeed, positive immunostaining for pAKT, pERK, PTEN and EGFRvIII has been reported to predict sensitivity to EGFR tyrosine kinase inhibitors in non-small-cell lung cancer and glioblastoma." (PMID 18628764, 2008). "In fact this is also the case for non-small-cell lung cancer resistance to the anti-EGFR TKIs." (PMID 18700047, 2008).